ELK3 (ETS transcription factor ELK3)
Description:
May be a negative regulator of transcription, but can activate transcription when coexpressed with Ras, Src or Mos. Forms a ternary complex with the serum response factor and the ETS and SRF motifs of the Fos serum response element.
Synonyms: SAP-2; NET; SAP2; ERP
Tractability: PROTAC: UniProt records ubiquitination sites on it; ubiquitination databases record sites on it; its protein half-life has been measured.
Target class: Transcription factor
Gene: Protein-coding gene on chromosome 12 (96,193,978 to 96,269,835, forward strand). Ensembl gene ENSG00000111145.
Subcellular location: Nucleus
Subcellular location (Human Protein Atlas): Nucleoplasm; Mitochondria
Gene Ontology:
Molecular function: DNA-binding transcription activator activity, RNA polymerase II-specific; DNA-binding transcription repressor activity, RNA polymerase II-specific; protein binding; purine-rich negative regulatory element binding; RNA polymerase II cis-regulatory region sequence-specific DNA binding; sequence-specific double-stranded DNA binding; DNA-binding transcription factor activity; DNA-binding transcription factor activity, RNA polymerase II-specific; DNA binding; sequence-specific DNA binding
Biological process: negative regulation of transcription by RNA polymerase II; positive regulation of transcription by RNA polymerase II; cell differentiation; regulation of transcription by RNA polymerase II; signal transduction; negative regulation of DNA-templated transcription; regulation of DNA-templated transcription
Cellular component: nucleoplasm; nucleus; chromatin
Genetic constraint (gnomAD): Loss-of-function variants: 10 observed, 27.88 expected, observed/expected ratio (o/e) 0.36, 90% interval 0.22 to 0.61. The upper end of that interval is the gene's LOEUF score, 0.61, which puts it in group 2 of 6, group 1 being the genes least tolerant of losing a copy. Missense variants: 463 observed, 534.52 expected, observed/expected ratio (o/e) 0.87, 90% interval 0.8 to 0.94. Synonymous variants: 272 observed, 248.85 expected, observed/expected ratio (o/e) 1.09, 90% interval 0.99 to 1.21.
Homologues: Orthologues: chimpanzee ELK3 (99% identical), macaque ELK3 (99% identical), rabbit ELK3 (95% identical), pig ELK3 (94% identical), dog ELK3 (94% identical), rat Elk3 (93% identical), guinea pig ELK3 (93% identical), mouse Elk3 (92% identical), tropical clawed frog elk3 (80% identical), zebrafish elk3 (65% identical). Paralogues in human: ELK4 (51% identical), ELK1 (37% identical), ERF (22% identical), ETV3 (20% identical), ELF2 (20% identical), ELF4 (20% identical), ERG (19% identical), FLI1 (19% identical), FEV (18% identical), GABPA (18% identical), ELF1 (17% identical), ERFL (17% identical), and 16 more.
Diseases named in the same sentence as ELK3 in open-access papers:
ELK3 is named in the same sentence as 63 diseases in open-access papers, as found by Europe PMC text mining. Sharing a sentence is not in itself a finding about the gene and the disease. The quoted sentences say what the papers report.
breast carcinoma (20 papers, 2009 to 2025). "A study on ELK3-associated signaling networks in breast cancer tissues revealed that expression of ELK3 was correlated with AKT activation." (PMID 32104682, 2020). "Here, we report that miR-200a is a major determinant of the ELK3 mRNA level in different breast cancer subtypes, and that the miR-200a/ELK3 axis is functionally linked to the metastatic characteristics of TNBC cells." (PMID 32414208, 2020). "Overall, our findings provide evidences that miR-200a and ELK3 is functionally linked to regulate invasive characteristics of breast cancers." (PMID 32414208, 2020). "To understand the mechanisms underlying the difference of ELK3 mRNA level in breast cancer subtype, we first examined the methylation status of the ELK3 gene." (PMID 32414208, 2020). "In breast cancer, suppression of ELK3 in MDA-MB-231 cells resulted in the loss of metastatic characteristics, mainly by activating GATA binding protein 3 (GATA3) to regulate the expression of cell-cell adhesion factors and tight junctional proteins." (PMID 32104682, 2020). "Since this suggested that the tumorigenicity of MDA-MB-231 cells was increased by suppression of ELK3, we next examined other parameters linked to breast cancer progression." (PMID 27556500, 2016). "Furthermore, other groups have reported that ELK3 is linked to platinum drug sensitivity in ovarian and breast cancer." (PMID 37422450, 2023). "However, the mechanisms underlying the regulation of ELK3 expression during breast cancer metastasis are still ambiguous." (PMID 32414208, 2020). "Emerging evidence has demonstrated that ELK3 participates and acts as a critical oncoprotein in human cancers, including glioma, melanoma, gastric cancer, breast cancer, and PCa." (PMID 38632244, 2024). "Previous studies have demonstrated that ELK3 regulates breast cancer metastasis through Zeb-1, MT1-MMP, and GATA3 gene-mediated signaling pathways." (PMID 35409069, 2022). "Our previous study demonstrated that ELK3 repressed the expression of E-cadherin, a marker of epithelial cell, to trigger breast cancer metastasis." (PMID 35409069, 2022). "Elk3 has been shown to positively influence EMT in breast cancer cells as well as during progression of liver fibrosis." (PMID 34708244, 2022). "The expression of ELK3 in LECs promotes breast cancer progression and metastasis, suggesting that ELK3 is a key factor in regulating the tumor microenvironment and tumor-to-tumor communication and promoting cancer metastasis." (PMID 33828985, 2021). "In breast cancer cells, ELK3 promoted the cell migration and invasion by providing oncogenic miRNAs through exosomes." (PMID 34409034, 2021). "For instance, ELK3 suppression results in extensive changes in the expression profiles of breast cancer, thus decreases cell migration and metastasis during tumor progression." (PMID 34409034, 2021). "In recent years, ELK3 has been proven to play an important role in the occurrence and development of breast cancer, liver cancer, lung cancer, and other malignant tumors." (PMID 34233659, 2021). "Our previous studies demonstrated that ELK3 plays an essential role in inducing the migration and metastasis of breast cancer cells such as MDA-MB 231 cells." (PMID 32414208, 2020). "We found that miR-200a determines the expression level of ELK3 in breast cancer subtypes by directly targeting the 3’UTR of ELK3 mRNA." (PMID 32414208, 2020). "Our results suggest that, in the luminal and TNBC subtypes of breast cancer, the ELK3 mRNA level is mainly regulated at the post-transcriptional stage by miRNAs, rather than by DNA methylation." (PMID 32414208, 2020). "Here, as a follow-up study, we examined the molecular mechanisms underlying these differences and found that the expression level of the ELK3 mRNA in breast cancer subtypes is mainly determined by miR-200a." (PMID 32414208, 2020).
breast carcinoma (continued). "Overall, our findings reveal a novel functional link between miR-200a and ELK3 that critically impacts the tumor invasion phenotypes of breast cancers." (PMID 32414208, 2020). "Specifically, our data revealed that miR-200a is a major post-transcriptional regulator of ELK3 that determines its expression pattern in breast cancer cells." (PMID 32414208, 2020). "Next, we used published data from The Cancer Genome Atlas (TCGA) to analyze breast cancer patient samples and found that miR-200a expression was negatively correlated with that of the ELK3 mRNA in 747 breast cancer patient samples." (PMID 32414208, 2020). "We showed previously that the expression levels of the ELK3 mRNA and protein differ between subtypes of breast cancer; specifically, ELK3 expression is higher in the aggressive claudin-low type of triple-negative breast cancer (TNBC) than in the luminal type." (PMID 32414208, 2020). "In our previous studies, ELK3 expression was significantly correlated with cell migration and invasion in breast cancer, and ZEB1 regulated the transcriptional activity of ELK3 to repress E-cadherin expression in breast cancer cells." (PMID 32414208, 2020). "Quantitative analysis revealed that LECs expressed a significant amount of ELK3 that was comparable to that observed in the basal breast cancer cell line MDA-MB-231." (PMID 31182803, 2019). "ELK3 is highly expressed in various cancers, including basal-like malignant breast cancers, and it orchestrates metastasis during tumor progression." (PMID 31182803, 2019). "Suppression of ELK3 in another basal type breast cancer cell line, Hs578T, also accompanied with GATA3 activation as well as reduced migration and invasive capacity in vitro." (PMID 27556500, 2016). "We first examined ELK3 expression profiles in a cohort of 51 molecularly well-characterized human breast cancer cell lines." (PMID 27556500, 2016). "Of the genome expression profiles obtained by microarray analysis (all of which are deposited in the Gene Expression Omnibus data repository [GEO: GSE41313]), we compared that of ELK3 between the four breast cancer subgroups." (PMID 27556500, 2016). "The findings described herein indicate that ELK3 may play a previously unrecognized and important role in breast cancer metastasis based on data suggesting that its loss of function aids reprogramming of basal types of breast cancer cells to a less invasive, epithelial cell phenotype." (PMID 27556500, 2016). "Here, we show that ELK3 is overexpressed in a subset of breast cancers, in particular basal-like and normal-like/claudin-low cell lines." (PMID 27556500, 2016). "Indeed, Elk3 expression was up-regulated in breast cancer cells and liver cells following TGFβ treatment." (PMID 34708244, 2022). "In previous studies, ELK3 upregulation resulted in increased metastatic behaviour of breast cancer and liver cancer stem cells by enhancing cell migration and invasion, whereas its suppression led to a reversal of the epithelial-mesenchymal transition in breast cancer cells." (PMID 33980253, 2021). "Accordingly, the inhibition of ETS transcription Factor ELK3 (ELK3), which is frequently overexpressed in aggressive breast cancers, led to PI3K/AKT/mTOR activation, which in turn enhanced the chemosensitivity of MDA-MB-231 cells to doxorubicin by inhibiting protective autophagy." (PMID 34207792, 2021). "However, the molecular mechanisms involved in the regulation of ELK3 mRNA expression during breast cancer metastasis are still unclear." (PMID 32414208, 2020). "Notably, studies have shown that ELK3 regulates cell migration and invasion in hepatoma cells and breast cancer." (PMID 32571262, 2020). "To extend our understanding of the negative association between miR-200a and ELK3 in breast cancer, we analyzed the expression patterns of miR-200a, and the ELK3 mRNA in other breast cancer cells and human breast cancer patient samples." (PMID 32414208, 2020).
breast carcinoma (continued). "As an initial step to investigate the role of ELK3 in LECs during tumor development, we first examined the relative expression level of ELK3 in LECs compared to the basal type of breast cancer cells, in which ELK3 is highly expressed and plays an essential role in mediating metastasis." (PMID 31182803, 2019). "Since there is a prometastatic crosstalk between breast cancer cells and LECs6, we hypothesized that ELK3 in LECs regulates the expression of communication factors between LEC and tumor cells that promote tumor progression and metastasis." (PMID 31182803, 2019). "Therefore, we investigated whether the miR-200a/ELK3 axis controls the metastasis of breast cancer cells in vitro." (PMID 32414208, 2020). "Next, we transfected MDA-MB 231 cells with the candidate miRNAs and found that only miR-200a suppressed the endogenous ELK3 mRNA level significantly, suggesting that miR-200a might be the main factor that determines the amount of ELK3 mRNA in breast cancer cells." (PMID 32414208, 2020). "We suggest that miR-200a functions as a suppressor of metastatic characteristics by targeting ELK3 in breast cancers, and that the miR-200a/ELK3 axis determines the fate of breast cancer cells whether they are undergoing cell migration, invasion, or metastasis." (PMID 32414208, 2020). "Next, we determined whether the miR-200a/ELK3 axis regulates breast cancer metastasis in vivo." (PMID 32414208, 2020). "Our research group also reported that ELK3 activation mediated by RSK2 induces the transformation of JB6 Cl41 cells and the proliferation of breast cancer cells via regulation of c-fos gene expression." (PMID 38632244, 2024). "In this study, we investigated the role of ID4 in the metastasis of TNBCs within the framework of the ELK3 axis, which acts as a master regulator of EMT in various malignancies, including breast cancer." (PMID 38188675, 2023). "ELK3’s involvement in angiogenesis and its regulation of GATA3 expression, a crucial suppressor of metastasis, in breast cancer has also been documented." (PMID 38188675, 2023). "Correlation analysis of ELK3 and ID4 expression in breast cancer cells was performed using breast cancer cell line microarrays from GEO (accession code GSE41313)." (PMID 38188675, 2023). "Recently, several reports have suggested that ELK3 functions as an oncogene to regulate EMT-mediated metastasis in various cancers, including liver and breast cancers." (PMID 32414208, 2020). "We found that the expression levels of miR-200a and the ELK3 mRNA were negatively correlated in the luminal and TNBC subtypes of breast cancer cells." (PMID 32414208, 2020). "On the other hand, luminal-type breast cancer cells, including MCF7 cells, showed opposing patterns of ELK3 and miR-200a expression." (PMID 32414208, 2020). "We found that conditioned medium from ELK3-suppressed LECs (LCM) lost its ability to promote the migration and invasion of breast cancer cells such as MDA-MB-231, Hs578T and BT20 in vitro." (PMID 31182803, 2019). "In MDA-MB-231 breast cancer cells, knockdown of RSK2 or ELK3 suppressed cell proliferation with accumulation at the G1 cell cycle phase, resulting in inhibition of foci formation and anchorage-independent cancer colony growth in soft agar." (PMID 31018569, 2019). "Given that miR-135a targets ELK3’s 3′UTR in breast cancer, we propose investigating whether RHBDD1 transcriptionally regulates ELK3 using luciferase reporter assays." (PMID 40787199, 2025). "Unlike the data from the previous study on breast cancer, E-cadherin expression was no different between control and ELK3 overexpressed SNU484 cells." (PMID 35409069, 2022). "An in silico analysis of human breast cancer patient samples and breast cancer cells revealed a negative relationship between miR-200a and ELK3 expression." (PMID 32414208, 2020).
breast carcinoma (continued). "These inhibitory effects of RSK2 on the nuclear localization of ELK3 were also confirmed by the results obtained following RSK2 knockdown, as well as by chemical inhibition of RSK2 using kaempferol and BI-D1870, in MDA-MB-231 breast cancer cells." (PMID 31018569, 2019). "Additionally, we used western blotting to analyze the cellular content of ELK3 using HepG2 and MDA-MB-231 breast cancer cells." (PMID 31018569, 2019). "Therefore, we examined expression of ELK3, GATA3, and LOX by constructing a heat map matrix using public microarray data derived from breast cancer cell lines." (PMID 27556500, 2016). "A recent report shows that ELK3 drives malignancy in SCCs, suggesting that the role of ELK3 as a promoter of metastasis is not likely to be limited to breast cancer." (PMID 27556500, 2016).
triple-negative breast carcinoma (9 papers, 2019 to 2025). An invasive breast carcinoma which is negative for expression of estrogen receptor (ER), progesterone receptor (PR), and human epidermal growth factor receptor 2 (HER2). "In vitro and in vivo experiments suggest that miR-200a and ELK3 expression is functionally linked to the metastatic characteristics of aggressive triple-negative breast cancer cells." (PMID 32414208, 2020). "Significantly, ELK3’s activity is pivotal in the proliferation of triple-negative breast cancer cells and androgen-independent human prostate cancers." (PMID 38632244, 2024). "At the same time, ELK3 expression correlates well with cell migration and invasion in the triple-negative breast cancer cell model (MDA-MB-231), and the low expression of these proteins would favor the control of the cancer phenotype in MCF-7 cells." (PMID 36430510, 2022). "Similar to MDA-MB 231, the migration and invasion of Hs578T, another triple negative breast cancer cell line to express high level of ELK3, was affected by the expression of miR-200a and miR-200a/pcDNA3.1-Flag-ELK3." (PMID 32414208, 2020). "Notably, ELK3, as a target gene of microRNA in triple-negative breast cancer, plays a regulatory role in metastasis." (PMID 40787199, 2025). "Based on the finding that ELK3 promotes the metastasis of triple-negative breast cancer (TNBC), we investigated whether ELK3 regulates the extravasation of TNBC by forming the ELK3-ID4 axis." (PMID 38188675, 2023). "Besides MDA-MB-231 cells, the migration of other triple negative breast cancer cells such as Hs578T and BT20 was also promoted by LCM and the effect of LCM on the migration was significantly diminished by the suppression of ELK3 in LECs." (PMID 31182803, 2019).